IDO1 (indoleamine 2,3-dioxygenase 1)
Diseases named in the same sentence as IDO1 in open-access papers (continued):
Sharing a sentence is not in itself a finding about the gene and the disease.
depression (139 papers, 2010 to 2026). "Elevated Rho GDI2 protein expression in HIP microglia was observed in male indoleamine-pyrrole 2,3 dioxygenase (IDO1)-knockout mice, a model of inflammation-associated depression." (PMID 38350966, 2024). "IDO1/2 variants have previously been associated with depression, depression treatment outcomes, Crohn’s disease, and systemic sclerosis." (PMID 39596587, 2024). "When indoleamine 2,3-dioxygenase 1 is overactivated, tryptophan in brain tissue is used to generate kynurenine, which reduces 5-HT synthesis, an important cause of depression." (PMID 38681644, 2024). "These investigations highlighted the causative role of IDO1 polymorphism in the pathophysiology of depression mediated by immune stimulation." (PMID 36911716, 2023). "IDO1 has been seen as a central hub linking immune-inflammatory processes to the monoaminergic and glutamatergic systems implicated in depression." (PMID 36911716, 2023). "Deletion of brain-derived neurotrophic factor (BDNF) and upregulation of indoleamine 2,3-dioxygenase 1 (IDO1) are associated with depression severity in animals." (PMID 35711916, 2022). "The deletion of brain-derived neurotrophic factor (BDNF) and upregulation of indoleamine 2,3-dioxygenase 1 (IDO1) are associated with depression severity in animals." (PMID 35711916, 2022). "Indoleamine 2, 3-dioxygenase 1 (IDO1) has been implicated in the pathogenesis of depression, though its molecular mechanism is still poorly understood." (PMID 33591947, 2021). "Consistent with previous reports that depression is associated with increased IDO1 expression, qPCR analysis showed that CUMS treatment significantly upregulated IDO1 [T=5.237, P=0.006] in the DRN." (PMID 33591947, 2021). "High levels of IDO1 are associated with depressive behavior in rats as well as pain and depression in humans." (PMID 32582210, 2020). "Rag2−/− mice took longer to recover from lipopolysaccharide-induced depression than wild type mice, and this was associated to a sustained increased expression of IDO1 in their brains." (PMID 30102966, 2018). "Polymorphisms in the Ido1 gene are associated with both treatment efficiency of anti-depressants and symptomology of depression." (PMID 27142940, 2016). "A polymorphism in the promoter region of the Ido1 gene (rs9657182, CC genotype) is a risk factor for patients to develop depression after immunotherapy." (PMID 27142940, 2016). "There is a significant amount of research suggesting that elevated Ido1 and Ido2 is associated depression-like behavior and elevated Tdo2 expression is linked to Schizophrenia." (PMID 27142940, 2016). "In the Sequenced Treatment Alternatives to Relieve Depression (STAR*D) trial two common SNPs in the IDO1 gene were associated with treatment outcome for either citalopram or overall antidepressant treatment." (PMID 24567701, 2014). "Activation of the tryptophan degrading enzyme indoleamine-2,3-dioxygenase 1 (IDO1) is associated with the development of behavioral signs of depression." (PMID 23866724, 2013). "Highlighting the role IDO1/2 variants play in depression and the potential role they could have in SUD." (PMID 39596587, 2024). "Of significance, is the downregulation of Ido1 and Aldh2 in brains from Winnie mice, given IDO1's association with exploratory behavior, cognitive function, and depression, and Aldh2's role in detoxifying ROS and ethanol metabolism, processes relevant to neurodegeneration." (PMID 39015786, 2024). "In conclusion, our study had shed light on that gene polymorphisms as suggestive risk predictors and expression levels of IDO1 were involved in depression occurring during the acute stage of stroke and the TNF-α rs361525 polymorphism was associated with serum IDO1 levels." (PMID 36911716, 2023). "The polymorphism of the IDO1 gene is related to susceptibility to cytokine-induced depression." (PMID 37191427, 2023). "However, IDO1 SNPs have been linked to depression and reduced susceptibility to recurrent vulvovaginal candidiasis." (PMID 35045867, 2022).
depression (continued). "Moreover, a very recent metabolomics study using LC-MS indicated indoleamine 2,3-dioxygenase 1 (IDO1) as a therapeutic target for pancreatic cancer-associated depression." (PMID 36555820, 2022). "Though both inflammation and KP metabolism are implicated in the pathophysiology of depression, it is rather controversial as to whether inflammation is needed to drive the dysregulation of the KP activity (via IDO-1)." (PMID 36299996, 2022). "-1849C > A - IDO1 (rs3824259) have been linked to depression." (PMID 35045867, 2022). "Therefore, it is evident that the reduction of BDNF can cause depression-like symptoms in mice whereas the knockout of IDO1 has antidepressant-like effects." (PMID 35711916, 2022). "Therefore, as a key TRP metabolism enzyme, IDO1 plays a critical role in the pathogenic mechanisms of depression associated with the regulation of endogenous KYN and 5-HT biosynthesis." (PMID 33591947, 2021). "The IDO1 SNP rs9657182 is associated with cytokine induced depression whereas KAT III rs1272958 may affect KAT enzyme function in depression patients." (PMID 34205235, 2021). "Regarding Ido1, the gene encoding the rate-limiting enzyme of tryptophan metabolism and catalysed the oxidation of L-tryptophan to N-formylkynurenine, increased activity has been observed in the plasma of patients with depression and rats with anhedonia." (PMID 33374959, 2020). "Similarly, H. pylori, which has been associated with depression in women, has also been associated with elevated levels of the tryptophan-degrading enzyme, IDO1." (PMID 37588396, 2019). "Increased tryptophan metabolism towards the production of kynurenine via indoleamine/tryptophan-2,3-dioxygenases (DOs: Ido1, Ido2, and Tdo2) is strongly associated with the prevalence of major depressive disorder in patients and the induction of depression-like behaviors in animal models." (PMID 27142940, 2016). "Finally, we examined the effect of IDO1 gene-deficiency on depression-like behavior, the levels of TRP metabolites, and changes of 5-HT turnover in the frontal cortex after IFN-γ gene transfer." (PMID 27436416, 2016). "Our findings suggest that inflammatory pathways that lead to the activation of IDO1 may be novel therapeutic targets in patients suffering from inflammation-associated depression, e.g., as is the case during HCV or cancer therapy." (PMID 27436416, 2016). "However, our results suggest that HCV patients who have a high sensitivity for IDO1 induction by IFNs are more susceptible to the depression-related side effects of IFN-α therapy." (PMID 27436416, 2016). "Previous studies suggested that IDO1-mediated TRP metabolism may be implicated in the development of depression, a side effect of IFN-α therapy in HCV patients." (PMID 27436416, 2016). "Indeed, the elevated activity of proinflammatory IDO1 is closely linked with the modulation of immune and metabolic responses, as shown in studies conducted in a mouse model of induced lipopolysaccharide (LPS) and depression-like behavioral symptoms." (PMID 40507778, 2025). "Thirdly, due to the limitation of sample size, we did not further evaluate the severity of PSD and it could be interesting to understand if there is an association between gene polymorphisms, serum IDO1 levels and severity of depression in a larger study population." (PMID 36911716, 2023). "In conditions like stroke and traumatic brain injury, over-activation of IDO1-mediated oxidative KP metabolism and increased QA levels contribute to secondary damage associated in the peri-infract area and have been postulated to contribute to post-stroke depression." (PMID 34205235, 2021). "Increased IDO1 and IDO2 are indirectly linked to reduced serotonin levels, depression, and mood disorders." (PMID 40766249, 2025).
depression (continued). "The abnormal expression of TPH2 and IDO1 has been linked to 5-HT system dysfunction and mental disorders like depression, whereas upregulating TPH2 and IDO1 enhances tryptophan metabolism, exerting antidepressant-like effects." (PMID 40290020, 2025). "Changes in IDO1 and KMO and change in HAM-D24 score post-ECT were negatively correlated in subgroups of patients with unipolar depression (IDO1 only), psychotic depression and ECT responders and remitters." (PMID 39417574, 2024). "Lower serum tryptase levels and higher indoleamine 2,3‐dioxygenase 1 activity were significantly correlated with more severe depression." (PMID 38146805, 2023). "The metabolic enzyme indoleamine 2,3-dioxygenase (IDO1) has been suggested as a biological mediator of inflammation in the psychopathology of depression, with increased KYN in the tryptophan (TRP) metabolic pathway resulting in reduced serotonin." (PMID 37048423, 2023). "A severe imbalance of intestinal flora in depressed mice further leads to the significant increase of interferon-γ, TNF-α and Indoleamine 2, 3-dioxygenase 1 (IDO1) in the hippocampus of mice, aggravating depression-like behaviors." (PMID 37293204, 2023). "Future adequately powerful trials are necessary to elucidate the role of IDO1 associated with the post-stroke immune-inflammatory responses in the pathogenesis of PSD, especially depression during the acute phase of stroke, from different perspectives." (PMID 36911716, 2023). "The levels of IDO1 are mainly increased in microglia in the brains of mice with poststroke depression (PSD)." (PMID 37190515, 2023). "As discussed in this review, IDO-1 inhibition represents a druggable target for the treatment of depression, particularly geriatric depression, and dementia, particularly AD." (PMID 37371332, 2023). "IDO1 is a significant contributor to depression, and inhibiting IDO1 ameliorates depressive-like behaviors in mice." (PMID 37190515, 2023). "The role of the KP in the generation of immunotoxins and pro-oxidant species, such as 3-HK and QUIN, increases the putative therapeutic utility of IDO-1 inhibition beyond depression and dementia." (PMID 37371332, 2023). "IDO1, a therapeutic target in depression, metabolizes tryptophan to KYN and is upregulated during pro-inflammatory states induced by several cytokines (IL-1β, IL-6, IFN-α, TNF-α)." (PMID 35501309, 2022). "The first mechanism involves tryptophan depletion through over-activation of IDO1 which increases tryptophan catabolism and thereby reduces the levels of tryptophan, as well as suppressing the synthesis of 5-HT, hence resulting in depression." (PMID 35711916, 2022). "Previous studies identified IDO-1 as a critical modulator of depression- and anxiety-like behaviors induced by systemic inflammation." (PMID 36160165, 2022). "Our previous study demonstrated that upregulation of IDO1 shifted tryptophan metabolism away from 5-HT biosynthesis, contributing to the development of depression in chronic pain condition." (PMID 36588734, 2022). "Our previous study has shown that regulation of brain IDO1 by proinflammatory cytokines serves as a critical mechanism of comorbid pain and depression through regulating tryptophan metabolism." (PMID 36588734, 2022). "The activation of IDO1 changes the concentration ratio between Trp and Kyn, and thus IDO1 is closely related to several important physiological disorders, including cancer, inflammation, and depression." (PMID 36408235, 2022). "In an animal model of depression, the activation of IDO1 and increased levels of Kyn have also been measured." (PMID 36408235, 2022). "The present study supports the notion that IDO1 antagonizes BDNF effects at the behavioral level in depression." (PMID 33591947, 2021). "For example, treatment with LPS induces IDO1 expression along with sickness behavior, depression-like behavior, and cognitive deficits." (PMID 34273987, 2021).
depression (continued). "This new strategy is based on the prevention or reversal of depression-like phenotypes by targeting IDO1, whose activity and expression are pathophysiologically linked to imbalances in TRP metabolites in the brain." (PMID 33591947, 2021). "We investigated the molecular mechanism of IDO1 in depression by using the chronic unpredictable mild stress (CUMS) model in Ido1-/- mice and WT mice." (PMID 33591947, 2021). "We demonstrated that DRN is potentially the region regulated by IDO1 in 5-HT metabolism and hippocampal neurogenesis in mice with depression-like phenotypes." (PMID 33591947, 2021). "Pain and depression, alongside liver expression of IDO-1/IL-1β mRNAs, were found to have subsided following an i.t. administration of an IL-1RA." (PMID 32842609, 2020). "Overactivation of the IDO1 pathway in patients with chronic inflammatory diseases, or in patients treated with type I IFN, was proposed to cause depression via central serotonin depletion or increased production of neurotoxic Quin in the brain." (PMID 32970636, 2020). "Patients with depression are characterised by a decreased level of tryptophan and increased activity of IDO1 and TDO2, which converts tryptophan into kynurenine." (PMID 33374959, 2020). "We described the important link between IDO-1 upregulation, the IL-1β signaling pathway, serotonergic (hypoactive) and glutamatergic (hyperactive) transmission, and depression." (PMID 32842609, 2020). "DO induction is requisite for depressive-like behaviors as genetic knockout of Ido1 gene transcription (Ido1KO mice) inhibits inflammation-dependent depression-like behaviors." (PMID 27142940, 2016). "In such cases, very little was known about the involvement of IDO1 and the KP in the pathophysiology of stress-induced anxiety and depression until the present study." (PMID 27828964, 2016). "An alternative interpretation for the involvement of IDO1 in cytokine-induced depression is the generation of neuroactive TRP metabolites." (PMID 27436416, 2016). "An unfortunate consequence of Ido1 induction is elevated production and release of downstream neuroactive Kyn metabolites (QuinA and KynA) that mediate depression-like, anxiogenic, and adverse cognitive behaviors." (PMID 27799931, 2016). "Genetic deletion of IDO1 in mice abrogated both the increase in depression-like behavior and the elevation in TRP metabolites’ levels, and the turnover of serotonin in the frontal cortex after IFN-γ gene transfer." (PMID 27436416, 2016). "IDO1 mediated pain and depression in rodents with chronic limb joint inflammation and elevated IDO1 expression in brain hippocampus correlated with these responses." (PMID 27168185, 2016). "Our results suggest that M30 is neuroprotective against CORT-induced depression targeting elevated MAO activities that cause oxidative stress and neuroinflammation, resulting in IDO-1 activation, serotonin deficiency and neurodegeneration." (PMID 27870896, 2016). "A recent study examined the role of brain indoleamine 2,3-dioxygenase (IDO1) in the comorbidity of pain and depression." (PMID 25810926, 2015). "This study found that inhibition of hippocampal IDO1 activity attenuated pain-induced depression, thus providing further evidence that 5-HT signaling can exert control over the comorbidity of pain and depression." (PMID 25810926, 2015). "The data obtained in the present study suggest a novel mechanistic link between epilepsy and depression via IDO1 expression in the hippocampus." (PMID 24594021, 2014). "Taken together, these data indicate that upregulation of brain IDO1 is sufficient for the development of depression-like behaviors following ICV LPS." (PMID 23866724, 2013). "Previous studies established 10 ng LPS as an ICV dose sufficient to induce central IDO1 expression and transient sickness followed by detectable depression-like behaviors." (PMID 23866724, 2013).
depression (continued). "For our model, however, it should be noted that TDO2 activity is not impacted by the presence of 1MT, and therefore it is unlikely that TDO2 is compensating for decreased IDO1 activity and driving depression-like behavior observed in the current studies." (PMID 23866724, 2013). "Our previous work has demonstrated that IDO1 activation is necessary for inflammation-induced depression-like behavior following systemic immune challenge." (PMID 23866724, 2013). "We investigated the role of brain IDO1 in mediating depression-like behavior of mice in response to intracerebroventricular injection of saline or lipopolysaccharide (LPS, 10 ng)." (PMID 23866724, 2013). "Further, ICV LPS induced depression-like behavior concurrent with elevations in brain kynurenine, and IDO1 was required for this behavioral response." (PMID 23866724, 2013). "Our data also suggest that brain IDO1 activity is an important regulator of depression-like behavior following ICV LPS, since genetic deletion or pharmacological inhibition of brain IDO1 protected mice from LPS-induced depression-like behavior." (PMID 23866724, 2013). "Recent preclinical research has demonstrated that pharmacological inhibition of IDO1 enzymatic activity or genetic deletion of IDO1 abrogates inflammation-dependent behavioral changes that model depression." (PMID 23866724, 2013). "Our studies were designed to directly investigate the effects of brain IDO1 activity on neuroinflammation-dependent depression-like behavior." (PMID 23866724, 2013). "The IDO1/kynurenine pathway has been studied in various chronic inflammatory diseases, including arthritis, where overexpression of the enzyme has been observed, as well as in psychological disorders such as depression." (PMID 39857723, 2025). "In addition to the neuroinflammation and IDO1 activation, oxidative stress is also a mechanism involved in the pathophysiology of depression." (PMID 39467780, 2024). "In this study, PROEs restored the levels of tryptophan and kynurenine in plasma, increased the expression of 5-HT1A mRNA in the cortex, reduced the expression of 5-HT2A mRNA in the cortex, and reduced the expression of IDO1 mRNA in the cortex and duodenum of depression-model rats." (PMID 37762181, 2023). "In addition, tryptophan breakdown triggered by IDO1 is reported to contribute to cancer-related anemia, fatigue, depression, and decreased quality of life." (PMID 36653774, 2023). "The commonality of a disease mechanism (neuroimmunologically mediated neuroinflammation) and a related druggable target (IDO-1) across the two disorders of depression and dementia also raises the interesting possibility of depression (geriatric) and dementia (AD) being a single spectrum disorder." (PMID 37371332, 2023). "Moreover, it provides the innovative possibility of assessing IDO-1 inhibitors for depression and their capacity to delay or prevent the subsequent onset of AD." (PMID 37371332, 2023). "Further support for this hypothesis is found in the fact that LPS was unable to engender depression-like behaviour in IDO1 knockout mice, suggesting inflammation-induced depression is IDO-dependent." (PMID 35977923, 2022). "Indoleamine 2,3-dioxygenase (IDO1) is primarily located in microglia, which suggests that it can have a role in a range of neurodegenerative diseases, e.g., Alzheimer's and Parkinson's, plus mental disorders, including depression and schizophrenia." (PMID 36304965, 2022). "IDO-1 is a rate-limiting metabolic enzyme of the kynurenine pathway composed of several neuroactive metabolites including QUIN, an endogenous N-methyl-D-aspartate receptor (NMDAR) agonist implicated in depression and cognitive deficits." (PMID 36160165, 2022). "Since IDO1 plays a key role in the comorbidity of pain and depression in our previous study, we examined whether fluoxetine treatment would change the expression of 5-HT1A auto-receptors and IDO1 in the DRN." (PMID 36588734, 2022).